NUMA1 (nuclear mitotic apparatus protein 1)
Description:
Microtubule (MT)-binding protein that plays a role in the formation and maintenance of the spindle poles and the alignement and the segregation of chromosomes during mitotic cell division. Functions to tether the minus ends of MTs at the spindle poles, which is critical for the establishment and maintenance of the spindle poles. Plays a role in the establishment of the mitotic spindle orientation during metaphase and elongation during anaphase in a dynein-dynactin-dependent manner. In metaphase, part of a ternary complex composed of GPSM2 and G(i) alpha proteins, that regulates the recruitment and anchorage of the dynein-dynactin complex in the mitotic cell cortex regions situated above the two spindle poles, and hence regulates the correct oritentation of the mitotic spindle. During anaphase, mediates the recruitment and accumulation of the dynein-dynactin complex at the cell membrane of the polar cortical region through direct association with phosphatidylinositol 4,5-bisphosphate (PI(4,5)P2), and hence participates in the regulation of the spindle elongation and chromosome segregation. Also binds to other polyanionic phosphoinositides, such as phosphatidylinositol 3-phosphate (PIP), lysophosphatidic acid (LPA) and phosphatidylinositol triphosphate (PIP3), in vitro. Also required for proper orientation of the mitotic spindle during asymmetric cell divisions. Plays a role in mitotic MT aster assembly. Involved in anastral spindle assembly. Positively regulates TNKS protein localization to spindle poles in mitosis. Highly abundant component of the nuclear matrix where it may serve a non-mitotic structural role, occupies the majority of the nuclear volume. Required for epidermal differentiation and hair follicle morphogenesis (By similarity).
Synonyms: NMP-22; NUMA
Tractability: Antibody: UniProt places it where antibodies can reach, with high confidence; its Gene Ontology location is reachable by antibodies, with high confidence. PROTAC: UniProt records ubiquitination sites on it; ubiquitination databases record sites on it; its protein half-life has been measured.
Gene: Protein-coding gene on chromosome 11 (72,002,860 to 72,080,693, reverse strand). Ensembl gene ENSG00000137497.
Subcellular location: Nucleus; Nucleus, nucleoplasm; Nucleus matrix; Chromosome; Cytoplasm, cytoskeleton; Cytoplasm, cytoskeleton, microtubule organizing center, centrosome; Cytoplasm, cytoskeleton, spindle pole; Cytoplasm, cell cortex; Cell membrane; Lateral cell membrane; Cytoplasm, cytosol (Isoform 3); Cytoplasm, cytosol (Isoform 4)
Subcellular location (Human Protein Atlas): Nucleoplasm
Pathways (Reactome):
Cell Cycle: Mitotic Prophase; Recruitment of NuMA to mitotic centrosomes
Gene Ontology:
Molecular function: disordered domain specific binding; dynein complex binding; microtubule binding; microtubule minus-end binding; microtubule plus-end binding; phosphatidylinositol binding; protein binding; protein domain specific binding; protein-containing complex binding; tubulin binding; structural molecule activity
Biological process: anastral spindle assembly; astral microtubule organization; establishment of mitotic spindle orientation; microtubule bundle formation; positive regulation of chromosome segregation; positive regulation of chromosome separation; positive regulation of intracellular transport; positive regulation of microtubule polymerization; positive regulation of mitotic spindle elongation; positive regulation of protein localization to cell cortex; positive regulation of protein localization to spindle pole body; positive regulation of spindle assembly; regulation of metaphase plate congression; regulation of mitotic spindle organization; nucleus organization; positive regulation of BMP signaling pathway; positive regulation of hair follicle development; positive regulation of keratinocyte differentiation; meiotic cell cycle
Cellular component: cell cortex; cell cortex region; centrosome; chromosome; cortical microtubule; cytoplasmic microtubule bundle; extracellular exosome; microtubule bundle; microtubule minus-end; microtubule plus-end; mitotic spindle; mitotic spindle astral microtubule; mitotic spindle midzone; mitotic spindle pole; nuclear matrix; nucleoplasm; nucleus; plasma membrane; protein-containing complex; spindle microtubule; spindle pole; spindle pole centrosome; cytosol; lateral cell cortex; lateral plasma membrane; and 4 more
Genetic constraint (gnomAD): Loss-of-function variants: 60 observed, 228.72 expected, observed/expected ratio (o/e) 0.26, 90% interval 0.21 to 0.32. The upper end of that interval is the gene's LOEUF score, 0.32, which puts it in group 1 of 6, group 1 being the genes least tolerant of losing a copy. Missense variants: 2,501 observed, 2,707.8 expected, observed/expected ratio (o/e) 0.92, 90% interval 0.89 to 0.95. Synonymous variants: 1,013 observed, 1,092.7 expected, observed/expected ratio (o/e) 0.93, 90% interval 0.88 to 0.98.
Homologues: Orthologues: chimpanzee NUMA1 (99% identical), macaque NUMA1 (96% identical), dog NUMA1 (89% identical), rabbit NUMA1 (87% identical), pig NUMA1 (87% identical), guinea pig NUMA1 (84% identical), mouse Numa1 (82% identical), rat Numa1 (82% identical), tropical clawed frog numa1 (42% identical), zebrafish numa1 (27% identical), Drosophila melanogaster GCC185 (7% identical). Paralogues in human: GOLGA3 (14% identical), GCC2 (13% identical), CEP164 (10% identical).